ARG1 (arginase 1)
Diseases named in the same sentence as ARG1 in open-access papers (continued):
Sharing a sentence is not in itself a finding about the gene and the disease.
myocardial infarction (11 papers, 2020 to 2025). Gross necrosis of the myocardium, as a result of interruption of the blood supply to the area, as in coronary thrombosis. "For instance, Arg1 and Fn1 serve as markers of pro-fibrotic macrophages in murine myocardial infarction, where macrophages promote fibroblast activation by producing Arg1 and Fn1." (PMID 40953007, 2025). "Here, we investigated the contribution of RBC Arg1 to systemic l-arginine metabolism, NO bioavailability, and cardioprotection following acute myocardial infarction in vivo." (PMID 40729962, 2025). "It appears that Arg1 plays a role in the pathophysiology of myocardial infarction whereas Arg2 plays an immunosuppressive and protective role, at least in rodents." (PMID 39952693, 2025). "In a mouse model of myocardial infarction, YAP/TAZ deficiency reduced pro-inflammatory cytokines such as TNF-α and IL-6 while increasing Arg1 expression, ultimately improving infarct healing and cardiac function." (PMID 41346626, 2025). "The aim of this study was to investigate the specific role of RBC Arg1 in regulating systemic l-arginine metabolism, NO bioavailability, and cardioprotection following acute myocardial infarction (AMI) in vivo." (PMID 40729962, 2025). "In preclinical models of myocardial infarction, quercitrin administration improved cardiac remodeling by promoting M2-like macrophage polarization, characterized by upregulation of Arg1, Ym1, and Mrc1, and by enhancing mitochondrial oxidative metabolism and reducing intracellular ROS levels." (PMID 41346626, 2025). "For instance, Arg1 transcription is activated by FOXO4 in myocardial infarction." (PMID 35196182, 2022). "Interestingly, IL-1, IL-6, CCL2, and CCL3 expression was reduced, whereas Arg1, IL4Rα, and IL-10 expression were increased in macrophages incubated with exosomes derived from the myocardial infarction group." (PMID 35548775, 2022).
pulmonary hypertension (11 papers, 2013 to 2025). Increased pressure within the pulmonary circulation due to lung or heart disorder. "A microarray analysis revealed upregulation of Arg1 and downregulation of Ddah1, molecules whose altered expression has previously been associated with pulmonary arterial hypertension." (PMID 24303100, 2013). "In hemolytic disorders, such as sickle cell disease, thalassemia, or paroxysmal nocturnal hemoglobinuria, NO deficiency is caused by release of arginase-1 from erythrocytes, leading to consumption of L-arginine finally resulting in vasoconstriction and pulmonary hypertension." (PMID 34599427, 2022). "Previously, we identified a single nucleotide polymorphism (SNP) in the arginase‐1 (ARG1) gene, rs2781666 (T‐allele) that was associated with a decreased risk for developing pulmonary hypertension (PH) in a cohort of infants with bronchopulmonary dysplasia (BPD)." (PMID 27895230, 2016). "It was proposed that an upregulation of Arg1 in the lungs leads to an imbalance in l-arginine/NO availability, resulting in pulmonary hypertension and/or smooth muscle contraction as well as lung tissue remodeling." (PMID 39952693, 2025). "Since macrophage polarization plays a critical role in the development and progression of pulmonary hypertension, expressions of iNOS and Arg-1 and the marker of M1 and M2 macrophage, respectively, in the lung were determined by Western blot." (PMID 36071873, 2022). "In the original report by Yeager and colleagues, MDSCs detected in the peripheral circulation of patients with pulmonary hypertension were noted to have increased Arg1 transcripts, consistent with a detected increase in urea activity from isolated patient samples." (PMID 30081463, 2018). "Arg1 may also contribute to pulmonary hypertension by stimulating NO-independent pathways such as the polyamine synthesis pathway." (PMID 24303100, 2013). "Finally, there are a number of ways that identified MDSC and T cell populations may contribute to pulmonary hypertension through many of the previously discussed metabolic or signaling pathways, including Arg1, iNOS, STAT3, and PD-L1/2 activation." (PMID 30081463, 2018). "Furthermore, the genes driving neutrophilic activity and TGF-β binding/skeletal muscle development (WFIKKN1 and ARG1) have been shown to be activated and involved in COPD, pulmonary hypertension, and chronic airway inflammation." (PMID 39346910, 2024).
fibrosis (10 papers, 2009 to 2025). the formation of excess fibrous connective tissue in an organ or tissue in a reparative or reactive process. "In fact, arginase 1 has been associated with the onset and progression of fibrosis in cystic fibrosis and schistosoma infection." (PMID 22347510, 2012). "Fizz1+ Arg1+ macrophages are considered reparative M2 type that promote tissue fibrosis and dampen T-cell activation, leading to immunosuppression by locally depleting L-arginine." (PMID 39949667, 2025). "Sixth, coronary perivascular fibrosis in DOCA-salt mice is prevented or reduced by deletion of ARG1+/− or ARG2−/−, respectively." (PMID 23908657, 2013). "Additionally, Arg1 expression is involved in airway fibrosis and bronchial hyper-reactivity." (PMID 34834178, 2021). "The nNOS transgene prevented age-related increases in arginase-1 but did not influence TGFβ expression, indicating that the transgene may prevent age-related muscle fibrosis by inhibiting the arginase-dependent profibrotic pathway." (PMID 26009878, 2015). "The major findings of this study are the contributions of arginase (ARG1 and ARG2) to elevated blood pressure, impaired EC-dependent vasorelaxation, increased vasoreactivity to constrictor stimuli, and enhancement of coronary perivascular fibrosis in a model of DOCA-salt hypertension." (PMID 23908657, 2013).
Hyperglycemia (10 papers, 2016 to 2025). An increased concentration of glucose in the blood. "PNS, especially the high-dose PNS, remarkably increased M2 phenotype ratio in macrophages cultured with hyperglycemia, and the mRNA expression of Ym1 and arginase 1 in macrophages was also upregulated." (PMID 30151392, 2018). "Meanwhile, the expression of arginase 1 was slightly higher in group with NF-κB inhibitor pretreatment than in hyperglycemia group (p<0.05)." (PMID 30151392, 2018). "Meanwhile, PNS remarkably increased the protein expression of arginase 1 and decreased IκB-alpha phosphorylation and subunits of NF-κB p50 and p65 from macrophages in culture medium with hyperglycemia." (PMID 30151392, 2018). "Furthermore, female NOD mice with Arg1 inhibition had less incidence of developing hyperglycemia than PBS-treated NOD mice." (PMID 35887317, 2022). "Interestingly, we found that hyperglycemia inhibited IL-10-secreting M2-like macrophage polarization, as revealed by decreased Arg1 and Mrc1 gene induction accompanied by a decrease in STAT3 and STAT6 signaling pathway activation." (PMID 29081777, 2017). "In streptozotocin-induced T1D in wild-type mice, Schistosoma mansoni infection inhibits the breakdown of pancreatic islets and hyperglycemia through increased Arg-1 and Ym1 expression rather than through processes that rely on Treg, IL-4, IL-13, and IL-10." (PMID 40299229, 2025).
ischemia (10 papers, 2018 to 2025). A hypoperfusion of the BLOOD through an organ or tissue caused by a PATHOLOGIC CONSTRICTION or obstruction of its BLOOD VESSELS, or an absence of BLOOD CIRCULATION. "After myocardial ischemia-reperfusion, increased expression and activity of Arg1 in coronary endothelial and smooth muscle cells are closely associated with the development of ischemia-reperfusion injury." (PMID 36361836, 2022). "We evaluated SMA and found a significant increase of Arg1 expression in the ischemia group, while both Arg1-/- and Arg1 KD showed a significant decrease of Arg1 by immunohistochemical analysis." (PMID 40425583, 2025). "Comparing with the ischemia group, we found that Arg1 KO or KD effectively improved the contractile reactivity of SMA and increased intestinal blood flow." (PMID 40425583, 2025). "In contrast, while MCAO mediated ischemia lowered the number of Iba1+Arg1+ cells, the hUC-MSCs and curcumin combined treatment effectively aggrandized these anti-inflammatory phenotypes." (PMID 36829224, 2023). "As a key player induced by injury, Arg1 is directly involved in the inflammatory cascade response post-ischemia." (PMID 36361836, 2022). "ARG-1-expressing astrocytes were found previously in an ischemia model as well as in an autoimmune encephalomyelitis model, suggesting that ARG-1 in astrocytes may be a reactive response to pathological conditions." (PMID 30112701, 2018). "Although the expression of the M1 marker iNOS and the M2 marker ARG-1 suggested that EE may regulate microglial polarization during ischemia, this evidence is not sufficient to reflect the state of the cells themselves." (PMID 36969204, 2023).
multiple myeloma (10 papers, 2020 to 2025). "However, although CD64 is an activating FcR, these HDNs from myeloma patients were less effective in phagocytosis compared to healthy controls, which was caused by the increased expression of arginase-1, which is an enzyme that is immune inhibitory." (PMID 33105656, 2020). "These include expansion of myeloid-derived suppressor cells, which drive immunoevasion via mechanisms that include arginase-1-driven depletion of L-arginine, thus indirectly promoting myeloma cell survival and tumor progression." (PMID 36172163, 2022). "In multiple myeloma, neutrophils exhibit a reduction of their phagocytic ability and an immunosuppressive effect through arginase-1." (PMID 34201758, 2021). "It has not been investigated so far whether and to what extent myeloid ARG1 can regulate tumor progression in multiple myeloma." (PMID 36385153, 2022). "Treating human macrophages with FAC, we observed a switch toward a M2-like phenotype associated with an increased expression of anti-inflammatory markers such as ARG1, suggesting the establishment of an iron-mediated immune suppressive tumor microenvironment favouring myeloma growth." (PMID 32863212, 2020). "Indeed, arginase-1 inhibitors reactivated the HDNs of myeloma patients." (PMID 33105656, 2020). "Treatment for 24 hours with myeloma conditioned media obtained from OPM2 but not U266 HMCLs induced ARG1 in healthy HDNs, while nor IL6 neither LPS did not induce any change in the amount of intracellular ARG1." (PMID 32029833, 2020). "Moreover, through the expression of Arg-1, MDSC confers resistance to bortezomib in human myeloma cell lines, which can be reversed while using Arg-1 inhibitors that were shown to decrease the L-arginase activity in correlation with a reduction of tumor growth in multiple mouse models of cancer." (PMID 33418996, 2021).
Insulin resistance (9 papers, 2017 to 2026). Increased resistance towards insulin, that is, diminished effectiveness of insulin in reducing blood glucose levels. "Conversely, anti‐inflammatory macrophages, identified by increased expression of CD206+ and Arg1, mitigate insulin resistance and enhance GLUT4 expression by clearing apoptotic adipocytes and secreting anti‐inflammatory cytokines." (PMID 41509193, 2026). "Based on these findings, we hypothesized that macrophage M1 < M2 polarization is related to the EPO-induced renoprotective effects in sucrose-induced insulin resistance model rats and found that EPO decreased the M1 marker TNFα and increased the M2 markers Arg1 and IL10 in the kidney." (PMID 40943240, 2025).
metastatic tumors (9 papers, 2016 to 2025). "We determined if Arg1 was present in the primary or metastatic tumors in the xenotransplantation model." (PMID 27851813, 2016). "High exosomal Arg-1 levels were associated with positive lymph nodes and shorter RFS, suggesting that circulating Arg-1+ exosomes could more accurately indicate metastatic disease and recurrence risk than tissue or plasma Arg-1 levels alone." (PMID 39409917, 2024). "Exosomal Arginase-1 might be a better indicator of metastatic disease and prognosis than tissue or plasma Argianse-1." (PMID 38001706, 2023). "While classical markers, such as HepPar1, Arg-1, and GPC3, remain foundational for distinguishing HCC from benign lesions and metastatic tumors, their limitations in specificity and sensitivity underscore the need for combinatorial approaches." (PMID 40941632, 2025). "In agreement with our in vitro finding, administration of CFTRi significantly reduced Arg1 expression levels in MoMs, increased CD8+ T cell infiltration and their activation (GzmB+CD8+; CD69+CD8+ T cells) in early metastatic tumors." (PMID 38355776, 2024). "Exosomes reflected biologically relevant Arg-1 levels in metastatic HNSCC and emerged as potentially more accurate biomarkers of metastatic disease and RFS than tissue or plasma Arg-1 levels." (PMID 38001706, 2023). "Of note, even in advanced metastatic tumors (d14), MerTKi treatment reduced Arg1 expression in MoMs without affecting overall abundance of MoMs." (PMID 38355776, 2024). "Arginase-1 is also a biomarker of HCC that helps distinguish primary and metastatic tumors." (PMID 37637156, 2023).
pancreatic ductal adenocarcinoma (9 papers, 2019 to 2025). An infiltrating adenocarcinoma that arises from the epithelial cells of the pancreas. "In addition, we demonstrated that high serum levels of ARG1 in pancreatic ductal adenocarcinoma patients are associated with high ARG1 activity." (PMID 35069595, 2021). "Recent studies have clarified that activated neutrophils in pancreatic ductal adenocarcinoma patients release NETs, where arginase 1 (ARG1) interacts with cathepsin S to obtain enzyme activity, thereby exerting anticancer effects." (PMID 39925807, 2025). "Arginase 1 (ARG1) blockade in combination with immune checkpoint inhibitors promotes CD8+ T cells in pancreatic ductal adenocarcinoma (PDAC) in vitro." (PMID 38581001, 2024). "Arginase 1 (Arg1) deletion in myeloid cells reduces tumor progression and induces macrophage repolarization in a spontaneous pancreatic ductal adenocarcinoma (PDA) mouse model." (PMID 36727849, 2023). "Recently, suppressive M-MDSCs from pancreatic ductal carcinoma patients were characterized as STAT3+/ARG1+/CD14+ cells with a distinct gene signature in which STAT3 has a main role in driving MDSC function." (PMID 35069595, 2021). "(A) Representative image of RNA in situ hybridization (ISH) of ARG1 (red) and co-immunofluorescence staining of immune (CD45, green) and epithelial (E-cadherin [ECAD], magenta) cells in human pancreatic ductal adenocarcinoma (PDA)." (PMID 36727849, 2023). "Penny and colleagues also reported that pancreatic ductal adenocarcinoma produced TAMs expressing both M1 (IL‐1β, IL6, and TNF‐α) and M2 (CD163, CD206, and Arg1) markers." (PMID 37688511, 2023). "In patients with pancreatic ductal adenocarcinoma CD13hi PMN-MDSCs were identified that produce ARG1 and suppress alloreactive T-cell responses in ARG1-dependent manner." (PMID 32499785, 2020). "Indeed, Penny and colleagues also reported that pancreatic ductal adenocarcinoma-generated TAMs expressed both M1 (IL-1β, IL6, and TNF-α) and M2 (CD163, CD206 and Arg1) markers." (PMID 30927925, 2019). "Monocytes co-cultured with CAFs from pancreatic ductal adenocarcinoma have been shown to present with increased surface expression of specific M2-markers, e.g., CD163, CD200R, and CD206 surface receptors and up-regulation of ARG1, IL10, and TGFB1 genes." (PMID 31108906, 2019).
coronary artery disease (8 papers, 2016 to 2023). "Logistic regression analysis (binary model) in all subjects when coronary artery disease was used as a response variable and age, gender, BMI, arginase-1, nitrate, nitrite, and the 2 single-nucleotide polymorphisms of ATG7 were taken as independent variables." (PMID 35777002, 2022). "ARG1 inhibition recently entered clinical trials for use in ischemia-reperfusion injury in patients with coronary artery disease." (PMID 26515089, 2016). "For example, LFNG and ID3 were highly expressed in control samples, while ARG1 and IL1R2 were highly expressed in patients with coronary heart disease." (PMID 28903366, 2017). "Nor-NOHA or hydroxy-nor-1-arginine is an arginase-1 inhibitor currently under clinical investigation for the treatment of patients with coronary artery disease suffering from ischemia-reperfusion injury." (PMID 37513979, 2023). "However, CDKN2B-AS was involved in the pathogenesis of coronary artery disease by targeting miR-92a-3p through GATA2, MAP1B and ARG1 regulation." (PMID 29552296, 2018).
epilepsy (8 papers, 2018 to 2026). A brain disorder characterized by episodes of abnormally increased neuronal discharge resulting in transient episodes of sensory or motor neurological dysfunction, or psychic dysfunction. "Human arginase I (ARG1) (PDB ID: 3thj) was selected to be involved in this study as ARG1 can be indirectly involved in the epilepsy mechanism." (PMID 41386826, 2025). "The level of Iba1, Arg-1, iNOS before the establishment of epilepsy model wereno statistical difference." (PMID 35356535, 2022). "Results of immunofluorescent staining showed that pilocarpine caused a significant increase in the number of Iba-1+iNOS+ cells (M1) and Iba-1+Arg-1+ cells (M2) in rat hippocampus, indicating microglial activation in the rat model of epilepsy." (PMID 32206297, 2020). "One recent study reported that microglial-specific expression levels of M2 markers (Arg1, Ym1) were significantly downregulated at the early chronic phase in a pilocarpine-induced epilepsy model." (PMID 31680864, 2019). "Then, we measured the levels of Arg-1, CD68, iNOS and CD86 in the hippocampus 24 hours after epilepsy modeling." (PMID 35356535, 2022). "mRNA expression of iNOS and CD86 (both markers of the M1 subtype) was increased markedly in VPA-resistant epilepsy, whereas expression of Arg-1 and CD206 (both markers of the M2 subtype) was decreased significantly in VPA-resistant epilepsy compared with VPA-sensitive epilepsy." (PMID 34497517, 2021).
lung adenocarcinoma (8 papers, 2016 to 2025). A carcinoma that arises from the lung and is characterized by the presence of malignant glandular epithelial cells. "In lung adenocarcinoma tissues, arginase-1 localizes predominantly to CD66b+ neutrophils and inversely correlates with CD3+ T cells." (PMID 40358184, 2025). "In mouse models of lung adenocarcinoma, Arg1 expression is elevated in G-MDSCs and both lung adenocarcinomas and squamous tumors." (PMID 37277776, 2023). "Accordingly, in the patient samples arginase 1 expression was mainly localized in the granulocytic myeloid cells and significantly elevated in both lung adenocarcinoma and squamous tumors as compared to the controls." (PMID 30728077, 2019). "Moreover, the protein expression levels of Fasn, Shmt1, Arg1, and Hk2, that have important functions in cell proliferation and growth, were studied by Western blot analysis and these experiments confirmed their up-regulation in lung adenocarcinomas." (PMID 27602772, 2016). "We assess the effect of lung adenocarcinoma cells on TAM through detecting the expression of SHP2, p- STAT1, p-STAT3, p-STAT5, p-STAT6, IL-4, IL-10, Cathepsin-L, Cathepsin-S, Cathepsin-K and Arginase-1 in each group of THP1 cells cocultured with and without A549 cells by western blot." (PMID 38747738, 2024).